TMEM158 (transmembrane protein 158)
Diseases named in the same sentence as TMEM158 in open-access papers (continued):
Sharing a sentence is not in itself a finding about the gene and the disease.
glioma (continued). "Compared to lower grade gliomas with IDH1 mutation and non-1p/19q codeletion (IDH1-Mut-noncodel, LGG), TMEM158 mRNA expression was higher in lower grade gliomas with IDH1 mutation and 1p/19q codeletion (IDH1-Mut-codel, LGG)." (PMID 34992215, 2022). "However, reduced p-STAT3 levels were further observed in U87MG, U251MG, and TJ905 glioma cells in response to TMEM158 downregulation." (PMID 34992215, 2022). "Importantly, TMEM158 downregulation inhibited glioma cell growth and decreased the expression of p-STAT3 and Ki-67 in vivo." (PMID 34992215, 2022). "Additionally, lack of TMEM158 attenuated proliferation, migration, and invasion of glioma cells, TMEM158 content was higher in laryngeal cancer, and TMEM158 may play a role in modulating cell apoptosis in laryngeal cancer." (PMID 37970923, 2023). "The exact pathways that TMEM158 may regulate in glioma remain unclear." (PMID 34992215, 2022). "Similarly, glioma cells displayed higher colony formation efficiency after upregulating TMEM158." (PMID 34992215, 2022). "E-Ca was downregulated in TMEM158-overexpressed U87MG, U251MG, and TJ905 glioma cells, while N-Ca, vimentin, and Snail were upregulated." (PMID 34992215, 2022). "We found that TMEM158 mRNA expression increased with tumor grade, and its expression in IDH1-wild-type (IDH1-WT) gliomas of each grade was higher than that in IDH1-mutant (IDH1-Mut) gliomas." (PMID 34992215, 2022). "The RT-PCR results for glioma tissues also verified that TMEM158 mRNA was highest in WHO grade IV glioma tissues and lowest in WHO grade I glioma tissues." (PMID 34992215, 2022). "In addition, TMEM158 was overexpressed in U87MG, U251MG, and TJ905 glioma cells, E-Cadherin was downregulated while N-Cadherin, vimentin, and Snail was detected." (PMID 37936608, 2023). "We first performed RT-PCR and western blotting to determine the transfection efficiency of lentiviral overexpression (OE-TMEM158) and knockdown (shRNA-TMEM158-1, sh-1; shRNA-TMEM158-2, sh-2) and the expression of TMEM158 in U87MG, U251MG, and TJ905 glioma cell lines." (PMID 34992215, 2022). "The results revealed that p-STAT3 was significantly increased in TMEM158- overexpressing glioma cells, whereas total STAT3 levels did not vary significantly from that of β-actin." (PMID 34992215, 2022). "Furthermore, the expression of TMEM158 was higher in IDH1-wt glioma samples compared to IDH1-mut irrespective of grade, and increased expression was correlated with poor OS in glioma patients." (PMID 36425564, 2022). "Expression of TMEM158 was abundant in WHO grade III and IV glioma tissues." (PMID 34992215, 2022). "Given the assumption that TMEM158 has a unique role in GBM, analysis of glioma sample clinical information and mRNA expression data obtained from TCGA and CGGA indicated that TMEM158 expression was related to WHO glioma grades and was more highly expressed in GBM than in lower grade gliomas." (PMID 34992215, 2022). "Interestingly, regardless of tumor grading, human glioma samples that were IDH1-wild-type (IDH1-WT) exhibited higher expression of TMEM158 than those with IDH1-mutant (IDH1-Mut)." (PMID 34992215, 2022). "However, the roles of TMEM158 in glioma have not been explored." (PMID 34992215, 2022). "However, the functions of TMEM158 in glioma are not clear thus far." (PMID 34992215, 2022). "Importantly, our results also demonstrated that overexpression of STAT3 rescues the TMEM158 knockdown-mediated proliferation, migration, invasion, and EMT process, indicating that TMEM158 promotes the proliferation, migration, and invasion of glioma cells by activating STAT3 signaling." (PMID 34992215, 2022).
glioblastoma (5 papers, 2022 to 2024). The most malignant astrocytic tumor (WHO grade IV). "Additionally, TMEM158 has been demonstrated to be associated with the enhancement of proliferation of glioblastoma cells through the STAT3 signaling pathway." (PMID 39428922, 2024).
breast carcinoma (4 papers, 2017 to 2022). "Analysis showed that TMEM158 mRNA levels were higher in tumor tissues from patients with TNBC than in tumor tissues from patients with other types of breast cancer and from normal breast tissue." (PMID 35711843, 2022). "The present study evaluated the expression and prognostic relevance of TMEM158 in breast cancer patients from several databases." (PMID 35711843, 2022). "Although TMEM158 has been shown to be involved in tumor progression, little is known about the molecular function and expression of TMEM158 in breast cancer." (PMID 35711843, 2022). "To investigate the role of TMEM158 in breast cancer, we determined its expression profile in various breast cancer cell subtypes." (PMID 35711843, 2022). "Analysis of the TMEM158 gene in 60 patients with primary breast cancer showed no mutations." (PMID 35711843, 2022). "Quantification of TMEM158 expression in tumor and normal tissue samples of 60 individuals with primary breast cancer showed that, although TMEM58 expression is suppressed in 23% of tumors, it was upregulated in 15% 11, suggesting it may not be an oncogene in breast cancer." (PMID 35711843, 2022). "Finally, 6 genes (GOLGB1, TMEM158, CXCL8, MCM5, HIF1AN, and TSPAN31) were selected that could optimally predict the lung metastasis risk of breast cancer patients." (PMID 33378415, 2020). "Evaluation of TMEM158 expression in 10 breast cancer cell lines showed that TMEM158 was overexpressed in BT549 and HCC1187 cells, but was not expressed in MDA-MB-231 cells." (PMID 35711843, 2022).
laryngeal carcinoma (4 papers, 2022 to 2025). Carcinoma that arises from the laryngeal epithelium. "Their results suggest that miR-548ac also acts as a tumor suppressor, primarily by inducing apoptosis in LSCC cells through the suppression of TMEM158, a protein they found to be overexpressed in laryngeal cancer tissues." (PMID 40299445, 2025). "Furthermore, through bioinformatic analysis, it was identified that in laryngeal cancer, TMEM158 is regulated by miR-548ac, and miR-548ac overexpression decreased TMEM158 levels." (PMID 37936608, 2023). "However, miR-548ac levels are significantly lower in tissues with carcinoma of the larynx compared to adjacent normal tissues, a higher expression of TMEM158 is observed and acts as an oncogene." (PMID 37936608, 2023). "In laryngeal cancer, TMEM158 expression increased according to increasing TNM stage; patients with low TMEM158 expression had a significantly longer survival time than patients with high TMEM158 expression." (PMID 37936608, 2023).
triple-negative breast carcinoma (3 papers, 2020 to 2022). An invasive breast carcinoma which is negative for expression of estrogen receptor (ER), progesterone receptor (PR), and human epidermal growth factor receptor 2 (HER2). "The effect of TMEM158 on the proliferation, adhesion and invasion of triple negative breast cancer cells was assessed." (PMID 35711843, 2022). "TMEM158 (transmembrane protein 158) has been proposed to participate in anti-tumor responses and is differentially expressed in triple negative breast cancer." (PMID 33378415, 2020). "Our study provides further insight into the role of TMEM158 in triple-negative breast cancer, which may be an effective therapeutic target for triple-negative breast cancer." (PMID 35711843, 2022).
lung carcinoma (2 papers, 2016 to 2026). "In particular, SUSD2, CCND2, BCL2A1, and TMEM158 could be potential targets of JFK in human lung cancers." (PMID 27087825, 2016). "Approximately 50 TMEMs have been found to be deregulated and have been studied in lung cancer; some predominantly act as tumor suppressors (e.g., TMEM100 and TMEM196), while others function as oncogenes (e.g., TMEM14A and TMEM158)." (PMID 41596760, 2026).
melanoma (2 papers, 2015 to 2022). A malignant, usually aggressive tumor composed of atypical, neoplastic melanocytes. "We observed a specific association of SOX9 with TMEM158, TBX3, and FYB, suggesting that TMEM158, TBX3, and FYB are direct targets of SOX9 in melanoma." (PMID 25885555, 2015). "TMEM158 is upregulated by SOX9 but no clear role has been established for the gene in melanoma." (PMID 25885555, 2015).
non-small cell lung carcinoma (2 papers, 2015 to 2022). A group of at least three distinct histological types of lung cancer, including non-small cell squamous cell carcinoma, adenocarcinoma, and large cell carcinoma. "In a non-small cell lung cancer (NSCLC) line transfected with the gene TLSC1, TMEM158 expression was found upregulated and tumor properties of the cells were suppressed." (PMID 26239324, 2015).
prostate carcinoma (2 papers, 2022 to 2023). A carcinoma that arises from epithelial cells of the prostate gland. "The membrane protein TMEM158 is significantly downregulated in prostate cancer and is tightly associated with disease progression, anti-tumor immune infiltration, and patient survival outcome." (PMID 36387246, 2022). "COX regression-based screening identified the membrane protein TMEM158 gene as negatively associated with disease-specific and progression-free survival in prostate cancer patients." (PMID 36387246, 2022). "Most importantly, TMEM158 and R-Ras were associated with NK cell and Mast cell infiltration in prostate cancer tissues." (PMID 36387246, 2022). "TMEM158 downregulation was tightly associated with adverse clinicopathological categories and worse survival outcomes in prostate cancers." (PMID 36387246, 2022). "Correlation analysis showed a tight correlation of TMEM158 expression with the level of R-Ras gene expression, which was also significantly downregulated in prostate cancers." (PMID 36387246, 2022). "In this study, our analysis revealed that the expression of the membrane protein TMEM158 was significantly downregulated in prostate cancers." (PMID 36387246, 2022). "Experimentally, androgen treatment reduced TMEM158 expression, while androgen depravation in the culture media led to increased levels of TMEM158 expression in prostate cancer LNCaP cells." (PMID 36387246, 2022). "Our data showed that R-Ras expression was strongly correlated with TMEM158 expression (Spearman r = 0.558, p < 0.001), and both TMEM158 and R-Ras expression levels were significantly reduced in prostate cancer tissues." (PMID 36387246, 2022). "In prostate cancers, TMEM158 expression was significantly lower than in benign tissue compartments, which is different from other cancer types with TMEM158 upregulation." (PMID 36387246, 2022). "Consistently, androgen treatment suppressed TMEM158 expression in prostate cancer cells, while androgen deprivation led to TMEM158 upregulation." (PMID 36387246, 2022). "We also found that TMEM158 expression was suppressed by androgens in prostate cancer cells but increased after androgen removal from the culture media." (PMID 36387246, 2022). "Since the AR signaling pathway is critical in prostate cancer development and progression, we analyzed the correlation of TMEM158 expression and AR gene expression in six RNA-seq datasets generated from prostate cancer tissues with different stages." (PMID 36387246, 2022). "In a cohort of early-onset prostate cancer patients, TMEM158 expression levels were shown at a significantly lower level in late-stage tumors, higher Gleason scores tumors, and biochemically relapsed (BCR) cancers." (PMID 36387246, 2022). "In prostate cancer cells, TMEM158 expression was suppressed after androgen addition but increased after androgen removal." (PMID 36387246, 2022). "In this study, we identified the transmembrane protein TMEM158 as a potent prognostic factor for disease-free progression and disease-specific survival in prostate cancer patients." (PMID 36387246, 2022). "Consistently, in prostate cancer PC-3 subline cells with different metastatic potential, TMEM158 expression was significantly lower in highly metastatic than weakly metastatic subline cells." (PMID 36387246, 2022). "To confirm TMEM158 downregulation in prostate cancer tissues, we conducted an immunohistochemical study on a set of prostate tissue arrays containing nine benign and 40 malignant tissue sections." (PMID 36387246, 2022). "Likewise, it was reported that the expression of TMEM158 had a very negative correlation with the expression of the androgen receptor (AR), suggesting that the AR pathway negatively modulates the expression of TMEM158 in prostate cancers." (PMID 37936608, 2023). "Likewise, the expression of TMEM158 was significantly lower in highly metastatic prostate cancer cells than in cells with less metastatic capacity." (PMID 37936608, 2023).
prostate carcinoma (continued). "Androgen deprivation also increased TMEM158 protein levels in prostate cancer LNCaP cells." (PMID 36387246, 2022). "TMEM158 expression and clinicopathological parameters in prostate cancer patients." (PMID 36387246, 2022). "Our results suggest that TMEM158 expression is a potent prognostic factor for disease progression and survival outcomes and that TMEM158 might serve as a potential therapeutic biomarker for prostate cancer treatment." (PMID 36387246, 2022). "It is unknown if TMEM158 expression is altered in prostate cancers." (PMID 36387246, 2022). "However, there is no report about TMEM158 expression in prostate cancer yet in the literature." (PMID 36387246, 2022).
autoimmune disease (1 paper, 2023). A disorder resulting from loss of function or tissue destruction of an organ or multiple organs, arising from humoral or cellular immune responses of the individual to their own tissue constituents. "While autoimmune diseases have many similarities with cancer, there are many links and similarities in the pathogenesis of both, so we speculate that TMEM158 may be closely related to the development of JIA." (PMID 36755318, 2023).
cholangiocarcinoma (1 paper, 2022). A carcinoma that arises from the intrahepatic biliary tree (intrahepatic cholangiocarcinoma) or from the junction, or adjacent to the junction, of the right and left hepatic ducts (hilar cholangiocarcinoma). "In addition, TMEM158 upregulation was also noticed in other types of human cancers, as reported by others, including cholangiocarcinoma, esophageal carcinoma, head and neck squamous cell carcinoma, lung adenocarcinoma and squamous cell carcinoma, rectum adenocarcinoma, and stomach adenocarcinoma." (PMID 36387246, 2022).
metastatic cancer (1 paper, 2022). A carcinoma which has spread from the original site of growth to another anatomic site. "TMEM158 expression gradually decreased from normal prostate and benign hyperplasia to localized primary and metastatic cancer tissues." (PMID 36387246, 2022).
Nephroblastoma (1 paper, 2018). An embryonal neoplasm characterized by the presence of epithelial, mesenchymal, and blastema components. "TMEM158 is overexpressed in Wilms tumors (also known as nephroblastoma) with somatic mutations in catenin beta-1 gene suggesting a relationship between the Ras and Wnt signaling pathways." (PMID 30574087, 2018).
ovarian tumor (1 paper, 2015). "Statistical analysis using the student’s t-test showed that TMEM158 mRNA was significantly overexpressed in ovarian tumor tissues when compared with normal tissues (P < 0.001)." (PMID 26239324, 2015).
periodontitis (1 paper, 2024). An acute or chronic inflammatory process that affects the tissues that surround and support the teeth. "MR analysis corroborated the inferences drawn from scRNA-seq, identifying ten causal gene markers associated with periodontitis, including LIMA1, PEA15, TMEM158, CMTM6, PDP1, FFAR4, VAC14, and ENHO." (PMID 39830509, 2024).
renal cell carcinoma (1 paper, 2022). "In contrast, renal cell carcinomas, renal chromophobe carcinoma, and uterine corpus endometrial carcinomas showed a significant downregulation of TMEM158 expression compared to their benign counterparts." (PMID 36387246, 2022).
serous ovarian tumors (1 paper, 2008). "For example, TMEM158, HEG1, PLOD2 and ATP13A3, were recently found differentially expressed greater than 3-fold in a comparative analysis of primary cultures of normal ovarian surface epithelial cells and malignant serous ovarian tumors." (PMID 18687136, 2008).
tumor (24 papers, 2015 to 2026). "Membrane protein TMEM158 was initially reported as a Ras-induced gene during senescence and has been implicated as either an oncogenic factor or tumor suppressor, depending on tumor types." (PMID 36387246, 2022). "Tumor immune infiltration profiling analysis discovered a strong association of TMEM158 expression with NK cell and Mast cell enrichment." (PMID 36387246, 2022). "Consistent with previous reports that R-Ras is required for immune response, R-Ras and TMEM158 expression were also tightly associated with anti-tumor immune infiltration (NK cell and Mast cell)." (PMID 36387246, 2022). "However, only TMEM158 expression was significantly associated with multiple clinicopathological features, including tumor stage, lymph node invasion, residual tumor after surgery, PSA level, and Gleason score." (PMID 36387246, 2022). "Interestingly, both TMEM158 and R-Ras were associated with anti-tumor immune filtrations." (PMID 36387246, 2022). "Subsequently, TMEM genes expression of stromal cells in normal and tumor tissues was compared, and TMEM158, TMEM38B, VMP1 and TMEM45A were recognized as DEGs." (PMID 37265785, 2023). "TMEM158 was initially reported as a Ras-induced gene during aging and classified as an oncogenic or tumor suppressor depending on the tumor type." (PMID 36755318, 2023). "We found that downregulation of TMEM158 diminished tumor volume and weight compared with the sh-NC group." (PMID 37970923, 2023). "Taken together, these findings indicate TMEM158 is involved in tumor invasion and metastasis regulated by EMT through activation of both the canonical and non-canonical TGF-β signaling pathways." (PMID 35711843, 2022). "Matrigel transwell assays evaluating the potential roles of TMEM158 in tumor invasion and migration showed that both siRNA1 and siRNA2 significantly reduced BT549 and HCC1187 cell migration and invasion." (PMID 35711843, 2022). "Several studies have confirmed that overexpression of TMEM158 enhanced the growth, adhesion, and motility of tumor cells through the TGF-β and PI3K/AKT signaling pathway." (PMID 34992215, 2022). "Semi-quantitative data analysis demonstrated a significantly lower level of TMEM158 expression in tumor tissues compared to benign tissues, either in case-matched pairwise comparison or group cohort comparison." (PMID 36387246, 2022). "Our analysis revealed that immune infiltration profiles related to the expression levels of TMEM158 and R-Ras genes were very similar, with an overlapped anti-tumor immune filtration." (PMID 36387246, 2022). "The knockdown of TMEM158 reduced tumor growth in vivo in a nude mouse." (PMID 37936608, 2023). "Tumour-like CAFs (tCAFs): We observed strong differential expression of proliferation-, migration- and metastasis-associated genes (e.g., PDPN, MME, TMEM158 and NDRG1) as well as stress-response-associated genes (e.g., ENO1), and GAPDH in a small cluster (n = 786 cells)." (PMID 37463917, 2023). "In addition, TMEM158 is located on chromosome 3p21.3, a chromosomal region frequent lost in many types of cancer, suggesting that this region is likely contains multiple tumor suppressor genes 26-28." (PMID 35711843, 2022). "Gain- and loss-of-function assays indicated that overexpressed TMEM158 might participate in EMT by activating the TGF-β pathway, which in turn promotes tumor migration, invasion, and metastasis." (PMID 35711843, 2022). "Furthermore, TMEM158 knockdown inhibited tumor growth of HO-8910 cell line in nude mice highlighting the role of this protein in tumorigenicity." (PMID 30574087, 2018). "Next, we determined whether knockdown of TMEM158 in ovarian cells could reduce tumor growth in vivo." (PMID 26239324, 2015). "The R-Ras/TMEM158 pathway might be involved in anti-tumor immune infiltration." (PMID 36387246, 2022).